CASP8 (caspase 8)
Diseases named in the same sentence as CASP8 in open-access papers (continued):
Sharing a sentence is not in itself a finding about the gene and the disease.
prostate carcinoma (continued). "c-FLIP is a dominant-negative homologue of caspase-8 that acts as a natural inhibitor of death receptor signaling and its sustained expression may play a role in the development of castration-resistant prostate cancer." (PMID 36551505, 2022). "The two clusters showed significant differences in the expression of PRGs; CHMP2A, CHMP4C, CYCS, CASP6, CASP8, GPX4, and TIRAP have high expression levels in cluster B, suggesting that these genes may associate with poor prognosis in prostate cancer." (PMID 35813821, 2022). "In a previous study, Tsai and Chen prepared a highly stable catechin nanoemulsion from green tea leaf waste and reported that it was effective in inhibiting the growth of prostate cancer cells PC-3 with the IC50 being 8.5 μg/mL through activation of caspase-8, caspase-9 and caspase-3." (PMID 34071530, 2021). "Moreover, high caspase-8 expression was correlated with a worse prognosis in prostate cancer patients." (PMID 34482382, 2021). "We examined the protein levels of CASP8 in prostate cancer tissue microarrays (TMAs)." (PMID 33828176, 2021). "Likewise, CASP8 mRNA expression was significantly upregulated in prostate cancer when compared to benign prostate tissues in four independent clinical datasets." (PMID 33828176, 2021). "In addition, mRNA levels of CASP8 were higher in metastatic prostate cancer when compared to primary prostate cancer." (PMID 33828176, 2021). "We further evaluated CASP8 protein levels in prostate cancer tissues." (PMID 33828176, 2021). "In prostate cancer cells, however, evodiamine caused an elevation in the activities of caspase-3 and caspase-9, but not caspase-8, in PC3 and LNCaP cells; and of caspase-3, caspase-9, and caspase-8 in DU145 cells." (PMID 29690562, 2018). "In addition, it also activates apoptosis by the activation of both intrinsic (caspase-9) and extrinsic (caspase-8) apoptotic pathways in prostate cancer cells." (PMID 30563284, 2018). "Moreover, also docetaxel was shown to enhance TRAIL-induced apoptosis through caspase-8, caspase-9 and caspase-3 activation in different prostate cancer cell lines." (PMID 28758908, 2017). "Instead, we suggest the existence of complex feedback mechanism where secondarily activated caspase-8 can further cleave the effector caspases, additionally amplifying the caspase cascade in the prostate cancer cells treated with cisplatin/LA-12 and TRAIL combination." (PMID 29182622, 2017). "Given that apoptosis can also be induced in human prostate cancer cells via the interaction of Fas and FasL, we examined the involvement of this pathway in the augmented, caspase-8-dependent apoptosis of PC3 cells co-treated with ABT-263 and the caspase-9 inhibitor." (PMID 25333266, 2014). "This suggests that stratification of prostate cancer patients based on signature genes characterizing CASP8 T cells could help in selecting patients who would benefit from olaparib treatment, which is a subdivision of personalized treatment for prostate cancer." (PMID 40149637, 2025). "In summary, we found that tumor expression of cIAP1/2, cIAP2, Survivin, procaspase-8, cleaved caspase-8, procaspase-3 and caspase-7 expression correlates with clinicopathological features of prostate cancer, indicating that these proteins may constitute markers of local disease." (PMID 26507126, 2015). "Additionally, 23 prostate cancer tissues were analyzed for CASP8 mRNA expression." (PMID 23554680, 2011). "Apigenin has also been shown to induce extrinsic apoptosis by upregulating the expression of caspase-8, -3 and TNF-a in PC-3 cells and prostate cancer stem cell CSC (CD44 (+)) isolated from there (25 μM)." (PMID 37298192, 2023). "JNK activation triggers the caspase 8-mediated cascade to induce apoptosis, but JNK inhibition decreases cell proliferation and induces apoptosis in prostate cancer cells." (PMID 37375646, 2023).
prostate carcinoma (continued). "ANO1 knockdown significantly increased protease expression and activation of caspase-8, caspase-3, caspase-7, and PARP (poly ADP-ribose polymerase) in prostate cancer PC-3 cells." (PMID 29899325, 2018). "It was discovered before, that treatment of prostate cancer cells with paclitaxel and TRAIL resulted in greater processing of caspase-8, Bid, procaspase-9 and caspase-3, resulting in engagement of the mitochondrial pathway to apoptosis." (PMID 28758908, 2017). "Conversely, caspase 8 inhibitor Z-IETD-FMK blocked the apoptotic ability of EP to cleave PARP and an increase of sub G1 population in DU 145 prostate cancer cells." (PMID 25506265, 2014). "Artepillin C restores TRAIL sensitivity in TRAIL-resistant LNCaP prostate cancer cells by upregulation of TRAIL-R2, activation of caspase-8 and caspase-3, as well as the disruption of MMP." (PMID 23573148, 2013). "In both prostate cancer cell types, cell death induced by LCA appears to be at least partly dependent on the activity of initiator caspase-8." (PMID 23940835, 2013). "Artepillin C overcomes TRAIL-resistance in LNCaP prostate cancer cells by upregulation of TRAIL-R2, activation of caspase-8 and caspase-3, and the disruption of MMP." (PMID 24324518, 2013). "In this study, we further demonstrate that treatment with high doses of PL can activate caspase 8-initiated apoptotic signalling in both AR-expressing (LNCaP) and AR-null (PC3) prostate cancer cells." (PMID 17262078, 2007). "Therefore, we explored the spatial-specific expression characteristics of Anoikis genes and CASP8 in prostate cancer and the prognostic role in BCR of prostate cancer using multi-database and multi-omics data." (PMID 40149637, 2025). "Therefore, S_Alistipes_shahii/caspase 8/prostate cancer may be not a reliable causal inference." (PMID 39882449, 2024). "In addition, 5′-Epiequisetin significantly inhibited the progression of prostate cancer in mice, accompanied by regulating the protein expression of DR5, caspase 8, survivin, and cadherins in vivo." (PMID 36034825, 2022). "By immunohistochemistry, CASP8 protein was expressed at higher levels in prostate cancer tissues compared to non-cancerous and BPH tissues." (PMID 33828176, 2021). "We further compared the mRNA levels of CASP8 between patients with recurrent and non-recurrent prostate cancer." (PMID 33828176, 2021). "We further analyzed the mRNA levels of CASP8 and S100A4 in four different prostate cancer datasets." (PMID 33828176, 2021). "Similarly, cryptocaryone also reportedly induced apoptosis in human prostate cancer PC3 cells in terms of the subG1 accumulation, cleavage of caspase-8 and 3, death receptor DR5 accumulation on membranes, and up-regulation of Mcl-1 expression." (PMID 26955958, 2016). "Protein expression of caspases (procaspase-8, cleaved caspase-8, procaspase-3, cleaved caspase-3, caspase-7 and procaspase-9) and IAPs (cIAP1/2, cIAP2, NAIP, Survivin and XIAP) was analyzed by immunohistochemistry in radical prostatectomy samples from 84 prostate cancer patients." (PMID 26507126, 2015). "An increase in the levels of cleaved caspase 8 in the PC3 tumor lysates from simvastation-treated mice indicate that one or both of the Fas-L and TNF-mediated death-receptor signaling pathway is involved in simvastatin-induced apoptosis in prostate cancer cells." (PMID 22974127, 2012). "The results indicate that caspase 8 and its downstream effectors participate in PL-induced apoptosis in prostate cancer cells, whether they express AR or not." (PMID 17262078, 2007).
prostate carcinoma (continued). "In addition, mRNA levels of CASP8 were higher in patients with recurrent prostate cancer when compared to patients with non-recurrent prostate cancer and high expression of CASP8 was associated with worse disease-free survival and overall survival in renal cancer." (PMID 33828176, 2021). "Consequently, we try to demonstrate here 3-azidoWA as well as TRAIL mediated inhibition of MMP-2 in cervical (data not shown) and prostate cancer cell line through induction of extracellular Par-4 which has been shown to induce extrinsic apoptotic pathway by FADD-caspase-8-caspase-3 activation." (PMID 22962598, 2012). "Paired with our observation that inhibition of caspase-8 did not completely abrogate LCA-induced cell death, it is likely that LCA induces both caspase-dependent and -independent modes of apoptosis in prostate cancer cells." (PMID 23940835, 2013). "However, the CASP8 D302H variant showed low-penetrance in Asians (minor allele frequency, MAF = 0% in Asians, MAF = 12.5% in Europeans based on the HapMap and Environmental Genome Project database), and we could not analyze the association with prostate cancer risk in this study." (PMID 23554680, 2011).
leukemia (66 papers, 2002 to 2025). A malignant (clonal) hematologic disorder, involving hematopoietic stem cells and characterized by the presence of primitive or atypical myeloid or lymphoid cells in the bone marrow and the blood. "The present study shows that FasL-induced cell death was completely impaired in caspase-8- and caspase-10-doubly deficient (I9-2e) Jurkat leukaemia T-cell lines." (PMID 21049020, 2010). "Another study demonstrated TSAIII-induced apoptosis of human leukemia HL-60 cells via cleaved-caspase-3, caspase-8, caspase-9, and PARP in a dose- and time-dependent manner." (PMID 36611961, 2022). "Literature elucidated that in HL-60 leukemia cells, BB promoted cell apoptosis by increasing caspase-8/9 expression and caspase-3 activation, then leading to Bcl-2 inhibition." (PMID 34771481, 2021). "A study showed that berberine induces apoptotic cell death via activation of caspase-3 and caspase-8 in HL-60 human leukemia cells." (PMID 33806918, 2021). "Both pathways directly activate caspase-3 or via caspase-8, which eventually leads to apoptosis in the human leukemia cell line." (PMID 32168739, 2020). "It has been demonstrated that the treatment of human leukemia cells (HL-60) with trichosanthin activates caspase 8, 9, and 3, involving both intrinsic and extrinsic apoptosis pathways." (PMID 32168739, 2020). "This resulted in a synergistic increase in caspase 8 and 9 when combined with quercetin or apigenin, and caspase 9 when combined with emodin or rhein in each investigated leukaemia cell line." (PMID 31360305, 2019). "Previous studies showed that YM155 induces caspase-8 dependent apoptosis, in human leukemia cells, through downregulation of Survivin and Mcl-1 and, in glioma cell lines to promote loss of mitochondrial membrane potential and release of AIF to the cytosol." (PMID 31591437, 2019). "Briefly, STC induced apoptosis in both leukemia and colorectal cancer cells by activating caspase-8, then acid SMase; the resulting depletion of glutathione caused an increase in reactive oxygen species (ROS) production, which led to neutral SMase activation." (PMID 29642569, 2018). "Honokiol induces apoptosis in chronic lymphocytic leukemia cells through activation of Caspase-8 and Bax, it also potentiates the cytotoxicity of anti-leukemia chemotherapeutic drugs." (PMID 29892225, 2018). "Our data indicate that ABIN1 protects human leukaemia T-cells by resisting the apoptosis induced by T. gondii ME-49 via inhibition of the activation of caspase-8." (PMID 29776374, 2018). "The incubation with AD0157 at concentrations of 1 μM or higher (5 and 10 μM), significantly enhanced the activities of the initiator caspase-8 and caspase-9, and the effector caspases-3/-7 in a dose-dependent manner in the different leukemia cells." (PMID 29163182, 2017). "Older studies of our group observed CASP9 and CASP8 activation after viscum treatment in different leukaemia cell lines." (PMID 28061770, 2017). "Caspase-8 is frequently down regulated in leukemia that results in chemotherapy resistance and impaired prognosis in patients." (PMID 24244478, 2013). "Smac mimetic BV6 enhanced TNF-induced cell death in leukemia cells in 2 different ways: necroptosis, when the cells were apoptosis resistant (FADD– and caspase-8–deficient), and caspase-8–dependent apoptosis in apoptosis-proficient cells." (PMID 22929310, 2012). "Diallyl disulfide, found in garlic, enhances expression of caspase-8, Fas and FasL in leukemia K562 cells." (PMID 22442660, 2012). "Human CD4+ Jurkat cells are commonly used in screening anti-HIV-1 drugs, but other reports have indicated dandelion root extract shows a selective induction of apoptosis through the activation of caspase-8 in human leukemia cells (Jurkat)." (PMID 22078030, 2011). "Changes in caspase-8 and caspase-3 activity in the two leukemia cell lines were markedly greater than those in the LO2 and T cells, mirroring the different fate of the four cell lines after treatment with sTRAIL:FeSOD." (PMID 21418589, 2011).
leukemia (continued). "Taken together, these results provide insight into the mechanism of apoptosis induction by PCI-24781 in leukemia by highlighting the roles of caspase-8, FADD and increased superoxide levels." (PMID 20145726, 2010). "Moreover, we found that some genes are also important for leukemia development (Jarid2, Metap2, Jak3, Pla2G15, Zfp384, Casp8 and Dpf2)." (PMID 37700325, 2023). "In addition, researchers (2020) mentioned a correlation between down-regulation of survivin and increase in caspase 8 and 3 in two human leukemia cell lines (K562 and KG1a)." (PMID 36033958, 2022). "STAT3 downregulation of Casp8 has also been shown in the human leukemia HL-60 cell line." (PMID 33557010, 2021). "The activation of caspases is essential for apoptosis; we tested the caspase-3 activity and detected caspase-3 activation, and during the blocking of caspase-3, caspase -8, and caspase -9, cell death was inhibited, indicating apoptosis in the leukemia cell line." (PMID 32587616, 2020). "When quercetin or apigenin were combined with cisplatin or cyclophosphamide, both caspase 8 and 9 activity were synergistically increased in all investigated leukaemia cell lines, consistent with caspase 3 and nuclear morphological assessments shown previously (P ≤ 0.05)." (PMID 31360305, 2019). "Finally, cladoloside C2 induced leukemia cell apoptosis by activating the Fas/CerS6/p38 kinase/JNK/caspase-8 pathway in lipid rafts." (PMID 29642569, 2018). "Hence, the majority of cytotoxic drugs routinely used in the treatment of leukemia exerts a therapeutic effect by activation of caspase-8." (PMID 24244478, 2013). "Little is known about the role of caspase-8; however, these results indicate that caspase-8 is crucial for the high anti-leukemic efficiency of numerous routine cytotoxic drugs, and it can be a promising pathway for the development of new therapeutic targets in leukemia." (PMID 37577033, 2023). "This hypothesis is supported by previous researches that showed intrinsic and extrinsic activation of Emilia sonchifolia extract on colorectal cell line and Solanum lyratum extract on leukemia cell line by increased bax and cleaved caspase-8, while decreasing caspase-8." (PMID 31118873, 2019). "However, our findings demonstrate activation and proteolytic processing of the initiator pro-caspase-8, which suggests that this cysteine protease may be important for eupatorin-induced cytotoxicity in leukemia cells." (PMID 25390937, 2014). "Notably, leukemia cells with a reduced expression of death receptor genes (Fas associated via death domain (FADD), BH3 interacting domain death agonist (BID), caspase 8 (CASP8), TNF receptor superfamily member 10b (TNFRSF10B)) have been associated with patients showing no response." (PMID 38397092, 2024). "In our study, we also confirmed the activation of caspase 8 in canine lymphoma and leukemia cells exposed to BITC, although the percentage of cells with active caspase 8 was lower than those with activated caspase 3/7." (PMID 34769202, 2021). "To confirm these results, we selected three key genes involved in leukemia (interferon-regulatory factor 1 [IRF1], Caspase 8, and specificity protein 1 [SP1]) to confirm the gene expression of those factors was regulated by USP39." (PMID 30898977, 2019). "In our study, 23-HUA increased proteins levels of cleaved caspase-8, -9, -3 and PARP indicating caspases activation as one of the main pathways of the 23-HUA induced apoptosis in HL-60 leukemia cells." (PMID 30551620, 2018). "Furthermore, isogarcinol, isoxanthochymol, and guttiferone E were shown to strongly induce apoptosis in the leukemia cell line CCRF-CEM through activation of caspase-3/caspase-7, caspase-8, and caspase-9." (PMID 36865482, 2023). "Furthermore, we performed a microarray assay and found that USP39 regulated the expression of diverse genes in human leukemia cells, including IRF1, Caspase 8, and SP1, which were validated by qRT-PCR experiments." (PMID 30898977, 2019).
leukemia (continued). "Indeed, our current studies demonstrate that GSK-3β mediates ER stress-induced lysosomal apoptosis in leukemia involving caspase-2-induced LMP and cathepsin B relocation, which result in caspase-8 and -3 activation." (PMID 26727221, 2016). "To investigate whether avicins can induce cell death via activation of the death receptor–Caspase-8 pathway, we exposed Jurkat cells and a promyelocyte leukemia cell line, NB4 cells, to various concentrations of avicin D for 24–72 h and analyzed the viability and activation of the Caspase-8 pathway." (PMID 20046832, 2009).